CTSG (cathepsin G)
Diseases named in the same sentence as CTSG in open-access papers (continued):
Sharing a sentence is not in itself a finding about the gene and the disease.
tumor (continued). "Immunofluorescence staining showed that cathepsins B and D were localized to the CSCs both within the tumor nests and peri-tumoral stroma (PTS) and cathepsin G was localized to the phenotypic mast cells within the PTS." (PMID 34621666, 2021). "Neutrophils can release neutrophil elastase, matrix metalloprotease 8 (MMP8), matrix metalloprotease 9 (MMP9), vascular endothelial growth factor (VEGF), cathepsin G and proteinase-3 to degrade the extracellular matrix (ECM) and promote tumor invasion." (PMID 33526991, 2021). "N2 neutrophils are characterized as a higher expression of pro-tumor factors to induce the immunosuppression in the tumor microenvironment, including CCL2, CCL5, neutrophil elastase (NE), and cathepsin G (CG), with a higher expression of arginase." (PMID 31010242, 2019). "Besides fMLP, ligands for FPR1 also include non-microbial endogenous host-derived peptides such as mitochondrial formylated peptides fMMYALF, fMLKLIV and fMFADRW, Annexin A1 and Cathepsin G, that may be released by necrotic cells within the tumor microenvironment." (PMID 27432059, 2016). "IL–20 induced the expression of N-cadherin, STAT3, vimentin, fibronectin, RANKL, cathepsin G, and cathepsin K, all of which are involved in cancer cell migration, EMT, and tumor-induced osteolysis." (PMID 26440411, 2015). "Other authors have linked carcinogenesis to AAT degradation by matrix metalloproteinases activated by neutrophil elastase, cathepsin G, and proteinase-3, ultimately resulting in the production of COOH-terminal fragments, which boosts tumor growth in vivo." (PMID 24886427, 2014). "In summary, our results provide novel important insights into cathepsin G functions and indicate that cathepsin G increases the strength of E-cadherin-mediated cell-cell adhesion in MCF-7 cells, with important implications for tumor development and metastasis." (PMID 19920860, 2009). "To discover whether CTSG influences the CRC growth cells in vivo, we conducted xenograft tumor development model." (PMID 37151875, 2023). "In primary tumor tissues, they have previously been shown to support tumor growth, invasion, and angiogenesis possibly due to release of ECM remodeling enzymes such as MMP-8, MMP-9, elastase, and cathepsin G." (PMID 35954395, 2022). "While the Cathepsin G–RAGE interaction is important for neutrophil cytotoxicity, we assumed that other interactions might also support the neutrophil–tumor cell synapse required for subsequent cell killing." (PMID 35453656, 2022). "Cytoplasmic staining of cathepsin G (brown) presents in few cells located within the microvessels within the immediate vicinity of the tumor that did not express the protein." (PMID 28611989, 2017). "Together, these reports indicate that TANs-derived cathepsin G may induce ECM remodeling and promote tumor progression and metastasis." (PMID 26819959, 2015). "However, because NETs are made of chromatin fibers decorated with antimicrobial proteins such as neutrophil elastase, cathepsin G, and MPO, it is very likely that NETs concentrate these factors to high local concentrations within the tumor microenvironment." (PMID 26819959, 2015). "Corresponding m/z from collagen type I alpha 2 (COL1A2), cathepsin (CTSG), elongation factor 1-alpha 1 (EEF1A1), EH domain-containing protein 2 (EHD2), epiplakin 1 (EPPK1), prelamin-A/C (LMNA), and prolargin (PRELP) showed higher intensity distribution in HND in comparison to LND tumour areas." (PMID 40603632, 2024). "There have been clear studies confirming that CTSG molecules play an important role in clearing pathogens and counteracting inflammatory responses, but there are no definitive studies on CTSG’s role in anti-tumor and promoting immune function." (PMID 39080685, 2024). "Albeit the Cathepsin G–RAGE interaction is dominant in neutrophil cytotoxicity toward many different kinds of tumor cells, we believe that other interactions may also contribute to neutrophil tumor recognition." (PMID 35453656, 2022).
tumor (continued). "While tumor RAGE interacts strongly with Cathepsin G expressed on the neutrophil cell surface, we did not observe any interaction between the CLRs and Cathepsin G (unpublished data), suggesting that another receptor on neutrophils is responsible for the binding of Cathepsin G to neutrophils." (PMID 35453656, 2022). "However, several studies have suggested that CTSG may be related to the regulation of body immunity, and the TCGA public dataset and the GEPIA2 database have shown that the expression of CTSG protein in both LUSC and LUAD tissues is significantly lower than that in non-tumor tissues." (PMID 39080685, 2024).
cancer (56 papers, 2014 to 2025). A tumor composed of atypical neoplastic, often pleomorphic cells that invade other tissues. "By reviewing related studies, it is suggested that Cathepsin G is associated with the host immune regulation and shows a role in inhibiting the development of other types of cancer." (PMID 39080685, 2024). "As unlimited growth is a cancer hallmark 32, we next investigate the role of CTSG in developing CRC." (PMID 37151875, 2023). "Cancer cell-derived G-CSF primes neutrophils, resulting in lytic NETosis; cathepsin G enhances NET-mediated cancer cell invasion among other NET-associated proteins." (PMID 35574410, 2022). "CTSG is also closely associated with various types of cancer." (PMID 35935989, 2022). "Recent studies have reported that cancer cells predispose neutrophils to generate neutrophil extracellular traps (NETs), which are web-like structures that help to capture platelets and increase TF activity by binding elastase and cathepsin G, thus contributing to cancer-associated thrombosis." (PMID 34769515, 2021). "Specifically, the clathrin coat assembly complex and SNARE proteins were among the top enriched genes essential for CTSG entering cancer cells." (PMID 41040318, 2025). "GO analysis showed that multiple nucleus export pathways and nuclear transport pathways are involved in CTSG-mediated cancer cell-killing function." (PMID 41040318, 2025). "To further verify that CTSG enters cancer cells through endocytosis, we stained early endosome marker, early endosome antigen 1 (EEA1), together with CTSG." (PMID 41040318, 2025). "The differentially expressed gene (DEG) analysis identified nine genes, including NTRK3 and CTSG, which are known to be involved in TiME in several cancer types." (PMID 39891665, 2025). "The main NET components, neutrophil elastase (NE) and cathepsin G (CG), activate dormant cancer cells by degrading the extracellular matrix (ECM) protein laminin." (PMID 38474175, 2024). "Chemotherapy induces neutrophil extracellular traps, which release cathepsin G that enters cancer cells, cleaves 14-3-3&epsilon;, and triggers apoptosis." (PMID 38194275, 2024). "TANs granules contain serine proteases, neutrophil elastase, MMP-9, and cathepsin G which induce cancer cells proliferation in AATs." (PMID 38969910, 2024). "The aim of this study was to examine the biological function and molecular mechanism of CTSG and to determine its potential as a cancer biomarker." (PMID 37588994, 2023). "Tumor necrosis factor (TNF) and cathepsin G derived from neutrophils promote distant metastasis of malignant tumors." (PMID 37143476, 2023). "NETs are decorated with a variety of proteins, among them neutrophil elastase (NE), cathepsin G (CG), and matrix metalloproteinase 9 (MMP-9), all of which have been implicated in cancer progression." (PMID 35267667, 2022). "Cathepsin G is also involved in perturbing E-cadherin-dependent cell adhesion, linking it to cancer cell migration and invasiveness." (PMID 33802262, 2021). "There is also evidence of Epi-1 modulating different genes in cancer cells, including necrosis related genes (calpain 5 and cathepsin G) and interleukin related genes." (PMID 31824449, 2019). "Both cathepsin G and cathepsin K play crucial roles in tumor-induced osteolysis, and they are also potentially a novel therapeutic target for treating cancer." (PMID 29690863, 2018). "We found that IL-20 is able to stimulate the growth, migration, and function as an upstream mediator to enhance MMP-9, MMP-12, cathepsin K, and cathepsin G secretion in cancer cells." (PMID 29690863, 2018). "Regulating CTSG's cell-killing function may benefit both cancer patients and inflammatory disease patients." (PMID 41040318, 2025). "We revealed here that CTSG released by NETs enters cancer cells through RAGE-mediated endocytosis." (PMID 41040318, 2025).
cancer (continued). "In this process, neutrophil-derived cathepsin G activates insulin-like growth factor-1 to promote the entry of cancer cells into the bloodstream, while NETs can capture circulating cancer cells and promote the colonization of cancer cells in distant organs." (PMID 40131539, 2025). "Furthermore, arrayed CRISPR/Cas9 screening targeting membrane trafficking genes indicated that vesicle organization and transport pathways were involved in CTSG entering cancer cells." (PMID 41040318, 2025). "Given that we have demonstrated in xenograft models that CTSG in the NETs plays a key role in killing cancer cells, we set to determine whether the same is true for the syngeneic models." (PMID 38194275, 2024). "Given that CCDC25 is reported to be a receptor for NET DNA, we tested whether CTSG enters cancer cells through CCDC25-mediated NET DNA-CTSG complex internalization." (PMID 38194275, 2024). "CTSG expression was significantly downregulated in the cancer group (p < 0.01)." (PMID 37588994, 2023). "The CTSG expression is elevated in cancer tissues than in adjacent cancerous tissues." (PMID 37151875, 2023). "Cathepsin G was found to be essential for neutrophil-supported lung colonization of cancer cells." (PMID 34572138, 2021). "Cathepsin G, a neutrophil-derived serine protease, induces cell migration, activates insulin-like growth factor 1, increases E-cadherin-mediated intercellular adhesion and cancer cell aggregation, and promotes cancer cell entry into blood vessels." (PMID 34674757, 2021). "IL-20 induces the expression of MMP9, MMP-12, RANKL, cathepsin K and cathepsin G in cancer cells." (PMID 29690863, 2018). "Recently, roles for cathepsin G in cancer cells have been reported." (PMID 29290980, 2017). "In this study, we investigated whether inhibition of cathepsin G could sensitize TRAIL-mediated apoptosis in cancer cells." (PMID 29290980, 2017). "For instance, cathepsin G induces cell migration, activates insulin-like growth factor 1 (IGF-1), increases E-cadherin-mediated intercellular adhesion and cancer cell aggregation, and promotes the entry of cancer cells into blood vessels." (PMID 40342932, 2025). "We demonstrated that CTSG entered cancer cells through RAGE-mediated endocytosis, and CTSG co-localized with early endosomes in cancer cells." (PMID 41040318, 2025). "Recent studies have revealed the role of several cathepsins in promoting or inhibiting various cancers (e.g., lung, ovarian, thyroid, and colorectal), including cathepsin B (CTSB), cathepsin L (CTSL), cathepsin G (CTSG), and cathepsin S (CTSS)." (PMID 38883596, 2024). "The interaction of cathepsin G, found on neutrophils, with the receptor for advanced glycation end products (RAGE), found on the surface of tumors, plays a critical role in the cancer-fighting abilities of neutrophils." (PMID 38590662, 2024). "CTSG enters cancer cells through cell surface protein RAGE and cleaves 14-3-3ε, which leads to BAX mitochondrial translocation and triggers apoptosis of cancer cells." (PMID 38194275, 2024). "Recently, it has been shown that NETs can act as scaffold for the release of factors with antitumoral activity, i.e., cathepsin G, or, in the opposite direction, promoting EMT in cancer cells, i.e., TGF-β." (PMID 38693312, 2024). "PRTN3, ELANE, CTSG and MMP9 are the serine proteases released by the activated neutrophils and have been reported to degrade ECM proteins and promote cancer cell invasion." (PMID 36686780, 2022). "Several proteins involved in carcinogenesis or leukemogenesis are increased for clinical responders (ANO6, CHI3L1, CTSG, ELANE and FGR), suggesting that the sensitivity to ATRA/VP additionally depends on more general functions involved in cancer development." (PMID 33946813, 2021). "From these data, we selected potential biomarkers of cancer including six upregulated proteins (RNF213, CTSG, PGLYRP1, RPL8, S100A8, S100A9) and two downregulated proteins (GPX1, TNS1)." (PMID 34361002, 2021).
cancer (continued). "Interestingly, certain repressed genes like B4GALT2, ELANE, CTSG, MLC1, NMP3, and SLC43A3 act as cancer suppressors, inhibiting malignant features and cancer development." (PMID 40986633, 2025). "To study whether RAGE is required for CTSG entering cancer cells, we incubated RAGE-KO and parental HCT116 cells with CTSG." (PMID 41040318, 2025). "The CTSG stable overexpression HT29 cells or knockdown RKO cells and different control cells were subcutaneously administrated into mice to generate xenograft cancers." (PMID 37151875, 2023). "CTSG, NLRP9, DFNB59, APIP, SCAF11, CASP5 and NAIP showed significant downregulation across cancers." (PMID 36605187, 2022). "CTSG is a well-established therapeutic target for both AML and ALL cancers." (PMID 34093641, 2021). "Six of these proteins had a higher abundance in cancer patients than in healthy controls (RNF213/ring finger protein 213; CTSG/cathepsin G; PGLYRP1/peptidoglycan recognition protein 1; RPL8/ribosomal protein L8; S100A8/S100 calcium binding protein A8; S100A9/S100 calcium binding protein A9)." (PMID 34361002, 2021). "We compared the expression of the 15 immune gene cancer tissues and adjacent tissues in the TCGA-BLCA cohort and found that the expression of the CCR9, IL7, PTGER4, IL10, CTSG, and ZBTB16 proteins in the adjacent tissues was significantly higher than that in the cancerous tissues (P < 0.05)." (PMID 32655621, 2020). "In this study, we found that inhibition of cathepsin G enhances TRAIL-mediated apoptosis in cancer cells but not in normal cells." (PMID 29290980, 2017). "Another neutrophil protease involved in cancer is cathepsin G. It has been shown to be a mediator of MMP-9 activation and promotes TGFβ (Transforming growth factor β) signaling that is important for formation of bone lesions, cancer-induced osteolysis and metastasis." (PMID 33802262, 2021). "Therefore, the combination of cathepsin G inhibition and TRAIL could be a therapeutic strategy for cancer therapy." (PMID 29290980, 2017). "However, the role of cathepsin G in cancer progression and cancer cell death is not fully understood." (PMID 29290980, 2017). "However, the knockout of CCDC25 did not impair the entrance of CTSG into cancer cells." (PMID 38194275, 2024).
infection (41 papers, 2005 to 2025). The state of being infected such as from the introduction of a foreign agent such as serum, vaccine, antigenic substance or organism. "Next, to evaluate a connection between host immune system activation and survival, we normalized protein abundance for infection-associated host proteins and observed a substantial increase in lipocalin-2, cathepsin G, and haptoglobin at 4 dpi for mouse #6." (PMID 41061967, 2025). "Cathepsin G (CatG), found in macrophages and PMNs, is a lysosomal protease that is upregulated in response to signals linked to infection and inflammation." (PMID 37998534, 2023). "Though cathepsin G and proteinase-3 can also contribute to pathology, it is the presence of elastase that is most associated with lung injury associated with infection." (PMID 28507954, 2017). "This is in agreement with previous studies showing divergence of human and mouse cathepsin G with respect to their substrate specificities, and normal infection of S. aureus in cathepsin G-deficient mice." (PMID 24130480, 2013). "Interestingly and further supporting the importance of the afEV cargo was the finding that cathepsin G, NE, and calprotectin knockout mice are all highly susceptible to infection with A. fumigatus." (PMID 32291301, 2020). "We can observe that the CTSG levels are significantly higher in the supernatants of MAP-infected CD14+-MDMs obtained from cows carrying the C allele (1.85 ± 0.11 ng/mL) after 2 h of infection than in infected CD14+-MDMs from cows with the AA genotype (1.68 ± 0.06 ng/mL) (p = 0.008)." (PMID 36359162, 2022). "It primarily protects cells from proteases released by neutrophils and activated mast cells during stress or infection, such as neutrophil proteases elastase, cathepsin G, chymase, and others." (PMID 37834061, 2023). "Cows with the AC genotype have significantly higher CTSG protein levels (1.85 ng/mL) in the supernatants of enriched CD14+-MDMs after 2 h of infection when compared with infected CD14+-MDMs from cows with the AA genotype (1.68 ng/mL)." (PMID 36359162, 2022). "Using dPLB cells, we identified extracellular vesicles containing cathepsin G and azurocidin; however, the distribution remained relatively equal between spontaneously released and infection-derived extracellular vesicles." (PMID 34986319, 2022). "Whereas thrombin is a major liver-derived enzyme, others such as cathepsin G and elastase are secreted from neutrophils during inflammation and infection." (PMID 34227939, 2021). "CTSG−/− mice were also investigated after infection with Mycobacterium bovis bacillus Calmette-Guérin (BCG) and showed an impaired pathogen elimination." (PMID 31727956, 2019). "Thus, the lack of a strong phenotype of SdgA/B deficient S. aureus bacteria in mouse infection may be explained by the possibility that mouse cathepsin G is either less effective in degrading unglycosylated SDR proteins or present at lower levels than in human phagocytes." (PMID 24130480, 2013). "Another study reported a remarkable upregulation of CTSG in murine infection with L. donovani." (PMID 38098491, 2023). "Our results confirm that an increase in CTSG mRNA expression correlates with higher levels of CTSG protein expression in the supernatants of MAP-infected CD14+-MDMs obtained from cows with the AC genotype following 2 h of infection." (PMID 36359162, 2022). "In the current study, we demonstrated that the heterozygous genotype for rs41976219 (AC) resulted in higher CTSG protein levels in the supernatants of infected MDMs after 2 h of infection and a significant lower intracellular MAP load at 7 d p.i. when compared with cattle with the AA genotype." (PMID 36359162, 2022). "At the site of infection, immune cells, such as neutrophils, infiltrate and become activated, releasing neutrophil serine proteases (NSPs), including cathepsin G (CatG), neutrophil elastase (NE), and proteinase 3 (PR3), which promote the mounting of a robust immune response." (PMID 35631327, 2022).